SETP12 (SET pseudogene 12)
Gene: Processed pseudogene on chromosome 4 (120,895,494 to 120,897,083, reverse strand). Ensembl gene ENSG00000251609.
Diseases named in the same sentence as SETP12 in open-access papers:
SETP12 is named in the same sentence as 1 disease in open-access papers, as found by Europe PMC text mining. Sharing a sentence is not in itself a finding about the gene and the disease.
SETP12 shares sentences with these, for which no sentence is quoted: infertile (1 paper).